IL6 (interleukin 6)
Diseases named in the same sentence as IL6 in open-access papers (continued):
Sharing a sentence is not in itself a finding about the gene and the disease.
COVID-19 (continued). "As diabetes has impaired T-cell function and increased interleukin-6, pneumonia-like symptoms can exist in these patients with COVID-19.23The association between COVID-19 and hypertension has generated considerable discussion." (PMID 36948200, 2023). "The severity of COVID-19 is associated with interleukin-6 (IL-6), C-reactive protein (CRP), and other proinflammatory factors." (PMID 38110869, 2023). "Elevated inflammatory markers are associated with severe coronavirus disease 2019 (COVID-19), and some patients benefit from Interleukin (IL)-6 pathway inhibitors." (PMID 37218940, 2023). "Dexamethasone has been shown to reduce COVID-19 related mortality, IL-6 inhibitors to reduce risk of cardiovascular or respiratory organ support, and baricitinib to reduce time to recovery in hospitalised patients requiring oxygen support." (PMID 37239131, 2023). "TNFα, IL1β and IL6 are known to be associated with post-acute sequelae of COVID-19 and used as biomarkers of SARS-CoV-2 infection in previous study." (PMID 36697403, 2023). "COVID-19-associated coagulopathy with microvascular thrombosis is secondary to inflammation and endotheliopathy that are “orchestrated” by IL-6, a pleiotropic proinflammatory cytokine." (PMID 36979908, 2023). "Severe cases of COVID-19 are associated with prolonged, heightened levels of cytokines, such as IL-6, IL-8/CXCL8, CXCL9, CXCL10, TNF-α, MCP1/CCL2, RANTES/CCL5, IL-18, and MIP-1α/CCL3, which can last for up to two months." (PMID 36983995, 2023). "IL-6 acts as a key mediator of cytokine storms caused by COVID-19; therefore, tocilizumab is used in severe cases of COVID-19." (PMID 37515030, 2023). "Increased levels of IL-6 and IL-10 were associated with a high risk of severe liver damage in COVID-19 patients." (PMID 37251383, 2023). "For early recognition of COVID-19-infected patients under imminent risk of acute respiratory failure, a sandwich format of IL-6 LFIA strip accompanied by a spectrum-based optical reader was developed." (PMID 37754132, 2023). "In this longitudinal study we aimed to investigate the association between Il-6 and disease severity of COVID-19." (PMID 37161412, 2023). "Increased levels of pro-inflammatory cytokines, especially IL-6, have been detected in the CSF of COVID-19 patients and have been implicated in neurologic diseases associated with COVID-19." (PMID 36899824, 2023). "Following the COVID-19 outbreak repeated IL-6 measurements in patients with COVID-19 and pneumonia were proposed as significantly lower serum IL-6 concentrations after admission were associated with a higher recovery rate." (PMID 37214473, 2023). "Proinflammatory and prothrombotic states in severe COVID-19 have been evaluated and increased ferritin and Il-6 were shown to be associated with poor outcomes." (PMID 38275989, 2023). "Interleukin-6 is a highly studied marker of immune activation in COVID-19, and its association with adverse outcomes (including the need for transfer to the ICU and death) was analyzed in systematic reviews." (PMID 36672715, 2023). "Prolonged high levels of IL-6 are correlated with severe COVID-19 outcomes in humans, and a similar association has been found in ferrets infected with SARS-CoV-2." (PMID 37552656, 2023). "Another study also showed that COVID-19 severity was linked with higher levels of proinflammatory cytokines in the first waves of the pandemic, with IL-8, IL-6, and IL-10 having the highest AUC values." (PMID 36766961, 2023). "Early studies confirmed that inhibiting IL-6 was a useful target in hospitalized patients with COVID-19-related pneumonia especially in the highest-risk group of patients." (PMID 36987476, 2023). "COVID-19 is associated with immune dysregulation and hyperinflammation, including elevated IL-6 levels." (PMID 37109231, 2023). "IL-6 can be utilized as a predictor for rapid identification of COVID-19 individuals at risk of illness progression." (PMID 36769328, 2023).
COVID-19 (continued). "In multivariate analysis with logistic regression analysis, risk factors for COVID-19 mortality in children were IL-6 levels with OR 18.570 (95% CI 5.320–64.803), ARDS OR 10.177, (95% CI 1.310–9.040) and AKI with OR 3.220 (95% CI 1.070–10.362)." (PMID 37889917, 2023). "IL-6 is a pro-inflammatory cytokine that regulates cell proliferation, differentiation, and apoptosis and has been implicated in the pathogenesis of COVID-19." (PMID 37896795, 2023). "High levels of ferritin, D-dimer, lactate dehydrogenase, and IL-6 were reported to be an indicator of poor prognosis and risk of COVID-19 mortality." (PMID 36919085, 2023). "Rationale: Interleukin-6 (IL-6), one of the main pivots in mediating inflammation in COVID-19, is associated with disease’s severity and mortality." (PMID 37311846, 2023). "When COVID-19 progresses to severe illness, higher serum levels of IL-6, CXCL8, TNF-α, and IL-1β are associated with hyperinflammatory and hyper-coagulable conditions." (PMID 37908356, 2023). "Higher lymphocyte (B= -0.003, P=0.004) and Albumin (B= -0.252, P=0.036) had lower risk and better outcome of hospitality for COVID-19 patients, while IL-6 (B=0.004, P=0.045) increased the mortality and poor recovery risk, predict the unsatisfactory outcome." (PMID 38095633, 2023). "The myocardial injury caused by COVID-19 was associated with multiple inflammatory pathways, and IL6, NFKBIA, CSF1, CXCL1, IL1R1, SOCS3, and CASP1 were key genes of the inflammatory pathway." (PMID 37564653, 2023). "Inflammation in COVID-19 patients is associated with up-regulation of interleukin (IL)-2, IL-6, IL-10, granulocyte colony-stimulating factor (G-CSF), interferon-inducible protein 10 (IP-10), monocyte chemoattractant protein 1 (MCP1)." (PMID 36814234, 2023). "So far, research has shown that COVID-19 patients with NAFLD have a distinct cytokine profile including increased levels of IL-6, IL-8, IL-10, and CXCL10, all associated with a more severe clinical presentation." (PMID 37375073, 2023). "Various studies have proposed the involvement of the IL-6/GM-CSF/JAK-STAT axis in developing COVID-19-associated cytokine release syndrome." (PMID 37021053, 2023). "COVID-19 patients with lung symptoms have more leukocytes and IL-6, which causes exacerbated inflammatory responses, cytokine storm, and organ failure accordingly." (PMID 37559103, 2023). "Risk factors associated with mortality in patients hospitalized for COVID-19 are age, male sex, tachypnea, low systolic blood pressure, low peripheral oxygen saturation, impaired renal function, elevated IL-6, elevated D-dimer, and elevated troponin." (PMID 37167338, 2023). "Some prognostic risk factors of COVID-19 severity have already been explored, such as age, diabetes, vitamin D deficiency, IL-6 levels, N-terminal pro-B-type natriuretic peptide (NT-proBNP) levels, and serum amyloid A levels." (PMID 37034572, 2023). "IL-6 is the cardinal cytokine implicated in the immunopathogenesis of CS, also serving as a predictor of COVID-19 clinical outcomes and mortality." (PMID 37371831, 2023). "It has been shown that severe COVID-19 is associated with a significant derangement in proinflammatory cytokines, namely, IL-1β, IL-2, IL-6, IL-8, or TNF-α, often referred to as the “cytokine storm”." (PMID 37762549, 2023). "COVID-19 can cause acute respiratory syndrome with consequent release of proinflammatory cytokines, including interleukin-1β (IL-1β) and IL-6, from the respiratory tract." (PMID 36752623, 2023). "Our data corroborate the previously reported increase in antiviral/proinflammatory cytokines IFN-α, TNF, IFN-γ IL-1, IL-6, IL-8, IL-17, and IL-33 in COVID-19, confirming the association between high IL-6 levels and disease severity." (PMID 37174682, 2023). "Salivary and serum interleukin-6 levels were significantly associated with COVID-19 severity (P values: 0.002 and 0.004, respectively)." (PMID 37568161, 2023).
COVID-19 (continued). "Excessive systemic inflammation and elevated IL-6 levels resulting from dysregulated host immune responses are associated with adverse clinical outcomes in patients hospitalized with COVID-19." (PMID 37384095, 2023). "Evidence suggests that elevated levels of pro-inflammatory cytokine interleukin 6 (IL-6) were associated with the disease severity of COVID-19." (PMID 37051002, 2023). "In the cytokine storm that characterizes the most severe types of COVID-19, IL-6 appears to be crucial in causing both systemic and localized hypercoagulable states." (PMID 36851766, 2023). "In this study cohort, we experienced one patient with COVID-19 due to Omicron variant who presented prolonged IL-6 elevation with deteriorated pulmonary lesions and subsequently required > 2 months of corticosteroid administration." (PMID 37376606, 2023). "Our findings confirm a defined cytokine signature in severe COVID-19 (with elevated IL-2, IL-6, TNFα, IL-1β and IL-10), and add further evidence to the role of IP-10, G-CSF and IL-33 in the cytokine milieu associated with severe COVID-19." (PMID 37063871, 2023). "Infections associated with COVID-19, however, have been associated with high serum levels of IL-6, CXCL8, and CXCL10." (PMID 37109156, 2023). "It has been established that high serum IL-6 levels are positively associated with more severe clinical courses in COVID-19 patients." (PMID 37251383, 2023). "The severity of COVID-19 and death were associated with increased levels of diverse cytokines, such as tumor necrosis factor–α and IL-6,67 suggesting a possible association with sustained autoimmunity." (PMID 37801317, 2023). "Studies have shown that IL6 is the most critical mediator in COVID-19 and is closely associated with poor prognosis and mortality." (PMID 37274117, 2023). "Previous studies have found that MSD has the widest dynamic range compared with other immunoassays for measuring IL-6 levels and that the Roche IL-6 assay is associated with clinical outcomes in COVID-19." (PMID 37650680, 2023). "Its results underlined a statistically significant correlation between COVID-19 severity and the IL-6, IgG, neutrophil count, % neutrophils, NLR, PLR, CRP, AST, and urea." (PMID 36838284, 2023). "Recently, some studies also found ACEI/ARB can significantly reduce COVID-19 caused pulmonary inflammation by inhibiting the levels of IL-6, C-reactive protein and calcitonin." (PMID 36634085, 2023). "has reported higher IL-6 and IL-10 levels in serum of adults over 65 with COVID-19, associated with disease severity and a higher comorbidity index." (PMID 37359549, 2023). "In previous studies, increased TNF-α, IL-1Ra, IL-6, IL-8, IL-15 and IL-10 serum levels were associated with higher mortality in COVID-19." (PMID 37969879, 2023). "In our cohort, the laboratory parameters associated with the severity of COVID-19 were a lower number of platelets or lymphocytes, a higher number of neutrophils, and elevated levels of ferritin or IL-6." (PMID 37626797, 2023). "Vaccination did not influence the levels of cytokine, chemokines, and hormones in our COVID-19 patients, except for a greater IL-6 response associated with vaccination, indicating an activated immune system." (PMID 37896963, 2023). "Serum ferritin, C-reactive protein (CRP), D-dimer, and interleukin-6 (IL-6) are examples of inflammatory markers that have been shown to be strongly linked to the high risks of developing severe COVID-19." (PMID 37575788, 2023). "Logistic regression analysis was applied to analyze the association between ACE-2 and IFITM-3 genetic variants, IL-6 profile, and COVID-19 severity." (PMID 38155729, 2023). "Regarding the hyperinflammatory response, elevated levels of pro-inflammatory interleukin-6 (IL-6) in COVID-19 patients have been associated with increased patient mortality, ICU admissions, and ventilator requirements." (PMID 37896963, 2023).
COVID-19 (continued). "The increase in inflammatory cytokines (e.g., IFN and IL-6) in COVID-19, together with other factors, such as genetic susceptibility, severity of COVID-19, and physiological stress, should play a role in casing TE." (PMID 37176700, 2023). "This study shows that the treatment with Jusvinza was associated with a decrease in IL-6 and several biomarkers of inflammation and coagulation in critically ill patients with COVID-19." (PMID 36730325, 2023). "It is also plausible that COVID-19 patients with lower miR-146a expression levels have higher levels of IL-6 and other pro-inflammatory cytokines, increasing the risk of cytokine storms." (PMID 37568870, 2023). "IL-6 trans-signaling is considered the main pathway of IL-6 signaling to LSECs and was implicated in endotheliopathy in COVID-19." (PMID 37376587, 2023). "The stability of the pooled results of the association between IL-6 levels and long COVID-19 was tested using a sensitivity analysis by excluding each individual study." (PMID 37095536, 2023). "In COVID-19, high levels of IL-6 have been associated with the severe form of the disease and worse prognosis of infection." (PMID 37138871, 2023). "Risk factors associated with mortality in patients hospitalized for COVID-19 are age, male sex, tachypnea, low systolic blood pressure, low peripheral oxygen saturation, impaired renal function, elevated IL-6 and elevated D-dimer." (PMID 37167338, 2023). "IL-6, as a marker of inflammation, has been linked with proteome changes consistent with an exacerbation of the acute phase response in COVID-19 patients and was successfully used as an adjunctive target therapy in critically ill patients." (PMID 38005844, 2023). "The data obtained not only contribute to a better understanding of the etiopathogenic mechanisms associated with COVID-19 outcomes but also strengthen the significance of IL-6’s biological role in the acute response to infection." (PMID 37818368, 2023). "Proinflammatory cytokine interleukin (IL)-6 was associated with disease severity in patients with COVID-19." (PMID 38030681, 2023). "Elevated IL-6 levels in patients recovering from COVID-19 have been associated with persistent symptoms, and a case report suggests that the IL-6 receptor antagonist, tocilizumab, ameliorates symptoms of PASC." (PMID 38090572, 2023). "Pulmonary edema, acute respiratory distress syndrome, and ventilatory dysfunction caused by COVID-19 are caused by the acute release of inflammatory cytokines IL-2, IL-6, IL-7, and TNF-α." (PMID 37175774, 2023). "A combination of elevated levels of PLA2 and IL-6 increased the risk of a severe infection and death of the patients from COVID-19 by 20.0 and 9.68 times." (PMID 36982611, 2023). "Down-regulation of SIRT 1 in COVID-19 is associated and highly correlated with elevated levels of IL-1β, IL-6, IL-8, and TNF-α." (PMID 37486805, 2023). "Both periodontitis and COVID-19 increase systemic inflammation levels and associated markers, such as IL-6 and CRP." (PMID 37568161, 2023). "According to recent research, IL-6 has been identified as a predictive factor for the early detection of COVID-19 patients who are at a heightened risk of experiencing worsening disease progression." (PMID 38106427, 2023). "Hyperinflammation is a hallmark of COVID-19 and is characterized by high levels of circulating proinflammatory cytokines, including interleukin-6 (IL-6), interferon-γ (IFN-γ), IL-1β, tumor necrosis factor (TNF), acute phase reactants, and ferritin." (PMID 38022199, 2023). "We conducted a non-adjusted Cox regression analysis to detect the relative risk of death among COVID-19 patients based on levels of IL-6." (PMID 37960722, 2023). "On the other hand, the logistic regression analysis of our data showed IL-6 on admission as a risk factor for COVID-19 severity (OR = 3.52, 95% CI [1.71–8.67, p = 0.002), and higher IL-6 levels were associated with aPI IgM positivity." (PMID 37626797, 2023).
COVID-19 (continued). "IL-6 is one of the most important proinflammatory factors associated with viral infections, and became a prognostic and diagnostic marker of COVID-19." (PMID 37298479, 2023). "In the total sample, chronic fatigue was associated with elevated pre-pandemic plasma IL-6 levels, which persisted after adjusting cytokine levels for age, sex, BMI, and COVID-19 status; chronic fatigue was as also associated with higher levels of BMI." (PMID 36995412, 2023). "The expression of caspase-4 in the lungs of COVID-19 patients showed an association with the levels of inflammasome activation markers such as caspase-1, IL-1β, IL-6 and IL-18." (PMID 37251383, 2023). "The study stated that male sex; smoking; and increased levels of D-dimer, lactate dehydrogenase (LDH), ferritin, and IL-6 are risk factors for PE in COVID-19." (PMID 37092518, 2023). "Recent reports have concluded that the imbalance between hyperinflammation and immune paralysis is a hallmark of sepsis and that the levels of inflammatory biomarkers such as interleukin 6 in patients with COVID-19 are associated with mortality." (PMID 37642512, 2023). "Due to the association of uncontrolled inflammation with severe COVID-19 and unfavorable outcomes, we investigated IL-6, IL-1β, and TNF as inflammatory markers in the respiratory track." (PMID 37752151, 2023). "In a systematic review and meta-analysis regarding the role of IL-6 in COVID-19, it was shown that higher levels of IL-6 were associated with poor clinical outcomes." (PMID 37189760, 2023). "The aberration in IL6 level was associated with COVID-19 complications, including neurological and cardiovascular diseases." (PMID 37564653, 2023). "One of the most comprehensive studies to date assessed plasma levels of these four cytokines in 1,484 hospitalised patients with COVID-19 and found robust associations between IL-6, IL-8 and TNFα levels and mortality – a finding widely replicated." (PMID 37063871, 2023). "Elevated IL-6 levels have been significantly linked to unfavorable clinical outcomes in COVID-19, such as the development of acute respiratory distress syndrome (ARDS) and mortality." (PMID 38139298, 2023). "IL-6 plays a crucial role in the cytokine storm, linked with COVID-19, forming hyper-inflammation and leading to the production of plasminogen activator inhibitor-1 (PAI-1), activator of the blood coagulation cascade." (PMID 36674665, 2023). "In COVID-19, an increase in IL-6 levels has been associated with the development of lung injury and hypoxemia, representing an important prognostic biomarker of severity." (PMID 36675573, 2023). "High levels of IL-6, associated with disease severity, have been widely described in COVID-19 patients." (PMID 37187739, 2023). "Specifically, interleukin-6 (IL-6) has been proposed to play an essential role in COVID-19-associated cytokine storms." (PMID 37405379, 2023). "Assessing individual risk factors, MAFLD presence, higher BMI, and elevated IL-6 showed statistically significant unfavorable effects of the COVID-19 outcome." (PMID 37629728, 2023). "Multivariate analysis showed that age, IL6, and hospital stay were factors influencing myocardial injury caused by COVID-19." (PMID 37564653, 2023). "Among the elevated cytokines in COVID-19 patients’ sera, IL-6 has been proven to be associated with CS." (PMID 37234160, 2023). "High levels of IL-6, associated with disease severity, have been widely reported in COVID-19 patients." (PMID 36730325, 2023). "In a randomized clinical trial involving 36 people with moderate to severe ARDS caused by COVID-19, alpha-1 antitrypsin was found to decrease IL-6 in serum." (PMID 37958192, 2023). "This study investigated the association between serum IL-6 levels, COVID-19 severity, and demographic, clinical, and biochemical characteristics." (PMID 37960722, 2023).